CD4 (CD4 molecule)
Diseases named in the same sentence as CD4 in open-access papers (continued):
Sharing a sentence is not in itself a finding about the gene and the disease.
co-infection (continued). "Among the 668 TB patients from the urban and rural settings in Tanzania we studied, patients from the rural setting were older, had a lower average BMI, and lower median CD4 cell counts in case of HIV co-infection." (PMID 29580279, 2018). "We found that co-infection suppresses CD4 + T-cell responses to protect against severe CHIKV-induced joint pathology, while disrupted B-cell affinity maturation in the spleen delays viral resolution in the joints." (PMID 30254309, 2018). "At baseline, patients with HIV-HBV coinfection had lower median CD4+ T-cell count than those of patients with HIV monoinfection." (PMID 30192795, 2018). "Only four studies showed the association for low CD4 count and five studies showed the association of Advanced WHO clinical stage with the outcome variable (TB/HIV co-infection)." (PMID 30281631, 2018). "As expected, co-infection resulted in a higher proportion (~ 2–3 folds) of late apoptotic CD4+ T cells in the pLN at 5 and 6 dpi." (PMID 30254309, 2018). "Why the median CD4 count in HIV/HCV co-infected study participants was higher than those with HIV/HBV co-infection was unclear." (PMID 34308161, 2017). "Our study predicts that the timing of viral clearance is determined by the timing of cART compared to the timing of HPV co-infection, as well as the CD4 T cell level." (PMID 28060843, 2017). "Baseline frailty index, current and nadir CD4 cell count, injection drug use, and HCV co-infection were associated with mortality in univariate analyses." (PMID 28981535, 2017). "When considering clinical characteristics, patients with chronic HCV co-infection or those with a CD4 cell count < 200 cells/mm3 were significantly more likely to report suicide risk, while those with chronic HBV co-infection were less likely to do so." (PMID 28192455, 2017). "The high prevalence of parasitic infection and correlation with decreased CD4+ concentrations highlight the need to re-examine the effects of invasive helminth co-infection in rural, HIV-infected populations in the era of widely available ART." (PMID 28542260, 2017). "Results of the Cox regression suggested that CD4+ cell count value < 350 cells/mm3 was strongly defined (hazard ratio = 15.4) by HCV co-infection and HIV-RNA values > 50 copies/mL in the previous examination (hazard ratio = 5.95)." (PMID 28166729, 2017). "Clinical variables significantly associated with suicide risk included low CD4 cell count and chronic HCV co-infection." (PMID 28192455, 2017). "HIV co-infection was detected in 139 (7%) patients; median CD4 cell count was 399 cells/μL (IQR 318–535)." (PMID 29073910, 2017). "Risk factors such as low CD4+ (cell count, high viral load at baseline, low CD4+ nadir, HCV-coinfection, drug abuse, and metabolic comorbidities are also associated with a higher incidence of HIV-neurocognitive impairment (cited in the following paragraphs)." (PMID 28383502, 2017). "Multiple HHV co-infections are common among ART-treated HIV-infected participants in the developing country setting and associated with persistent immune activation and poorer CD4 T-cell recovery." (PMID 29016635, 2017). "Among the 120 controls, one patient with malaria had human immunodeficiency virus (HIV) co-infection and was on antiretroviral therapy, with a CD4 count of 196 cells/μL and an undetectable HIV viral load at the time of malaria diagnosis." (PMID 28644847, 2017). "Equilibrium values for HIV RNA per ml and HIV-specific uninfected CD4+ T cells per ml were reported in an HIV/HPV co-infection study to be V ̄ = 4.8x104 virions per ml and T ̄ = 3.3x105 cells per ml." (PMID 28060843, 2017). "The influence of the number of HHV co-infection and K/T ratio on CD4 T-cell recovery was assessed using multivariate Poisson regression." (PMID 29016635, 2017). "Comparison with HIV/HBV co-infection revealed that the levels of CD4, ALT, and HBV DNA were significantly lower during occult infection." (PMID 28591184, 2017).
co-infection (continued). "We further examined group differences in mean CD4 count by co-infection status as well as ART status." (PMID 28346490, 2017). "Many predictors were important, with baseline frailty index, sex, current and nadir CD4 cell count, duration of HIV infection, duration of HIV exposure, injection drug use, HCV co-infection and smoking history all associated with outcomes after four years." (PMID 28981535, 2017). "Multivariate linear regression models showing the association of CD4 counts, HIV-pVL and presence of HCV coinfection, with different T-cells subsets in the whole population of patients." (PMID 28323897, 2017). "Econometric models indicate that HCV co-infection and HIV-RNA values >50 copies/mL in previous examinations are associated with CD4+ falls below 350 cells/mm3." (PMID 28166729, 2017). "Econometric models indicate that HCV co-infection and HIV-RNA load >50 copies/mL in previous examinations were associated with CD4+ falls below 350 cells/mm3." (PMID 28166729, 2017). "Our study highlights the impact of HIV co-infection on HCV specific CD4+ T cell responses in a unique cohort of patients for both HCV and HIV and suggests a crucial role for these cells in controlling chronic HCV replication and liver disease progression." (PMID 27455208, 2016). "We found missing data on level of education (1349, 13.1%), HIV transmission category (242, 2.3%), country of origin (218, 2.1%), CD4 count (775, 7.5%), VL (811, 7.8%), HCV coinfection (1081, 10.5%), and cause of death (47, 12.8% among death subjects)." (PMID 27603368, 2016). "Although mainly showing a proinflammatory instead of anti‐inflammatory cytokine profile 38, MTB/HIV‐1 coinfection is principally featured as immunosuppression due to CD4+ T cell depletion and subsequent reduction in antigen‐specific cytokine responses." (PMID 27113787, 2016). "To study progression from LTBI to active TB as a consequence of CD4+ T cell deficiency, as it occurs in HIV co-infection, we first adapted the murine ear dermis Mtb infection model." (PMID 27391012, 2016). "We find that as high as 44% of HIV-1-infected persons whose CD4+ T cell counts are <200/μL develop active TB after M. tb co-infection." (PMID 26959228, 2016). "In multivariate analysis, HCV co-infection, age, route of HIV infection, baseline CD4 count, baseline HIV RNA, and HIV-1 subtype were associated with immunological recovery." (PMID 26933963, 2016). "Significant risk factors affecting mortality included HCV co-infection, older age, late CDC stage, lower baseline CD4 count, higher baseline HIV viral load, and prior mono or dual ART." (PMID 26933963, 2016). "This is indicated by both the loss of CD4+ IFN-γ and IL-2 secreting cells and the increased frequency of PD-1 expression, which we observed in TB and HIV co-infection." (PMID 26756579, 2016). "CD4+ count recovery during ART has been shown to be initially blunted in individuals with co-infection as compared to those with HIV infection alone." (PMID 27251610, 2016). "Patients with HCV co-infection had significantly lower CD4 counts, worse CD4 cell recovery after 6 months of ART, and poorer survival than HIV mono-infected patients." (PMID 26933963, 2016). "Risk factors affecting mortality included HCV co-infection, age, CDC stage, baseline CD4 count, baseline HIV RNA and prior mono/dual ART." (PMID 26933963, 2016). "Co-infection with CMV was also a determinant of a lower probability to reach a CD4/CD8 ratio above 1 in a transversal study conducted in Paris." (PMID 27548257, 2016). "Study confirms that while residing in rural areas and presence of co-infection significantly increases the mortality risk among PLHIV, adherence to ART and improvement in CD4 counts led to significant reduction in their mortality risk." (PMID 27253974, 2016).
co-infection (continued). "Other independently associated variables included HBV co-infection (OR 2.37 for APRI, OR 1.91 for FIB4), CD4 count below 200 cells/μL (OR 2.55 for APRI, OR 2.28 for FIB4) and age ≥30 years (OR 1.80 for APRI, OR 8.81 for FIB4)." (PMID 26979535, 2016). "We found that the median CD4+T cell counts showed similar tendency with the total study population with different M. tb co-infection status." (PMID 26959228, 2016). "When we evaluate this results together, it is possible to notice that in Lb+Py co-infection, the increase in CD4+SP and CD8+SP occurred sooner than in La+Py group (10 and 17 dpi, respectively)." (PMID 27446022, 2016). "Our detailed dissection of the effects of HIV-TB co-infection on the MTB-specific CD4+ T-cell immune response has provided insight into clinically important features and indicated potentially useful immune correlates for monitoring disease activity." (PMID 26756579, 2016). "Progressive loss of CD4+ T cells, thought to stem from chronic immune activation is a major hallmark of HIV-1 co-infection." (PMID 26913028, 2016). "The mechanisms underlying this observation are likely to be multi-factorial, the lower HCV-specific T cell responses observed in HIV co-infection as a consequence of decreased CD4+ T cells are likely to have contributed." (PMID 27455208, 2016). "In summary, HIV co-infection with MTB was associated with a decrease in the amount of cytokine (IFN-γ, TNF-α and IL-2) secreted for HIV-specific CD4+ T cells." (PMID 25781898, 2015). "Different studies including our have clearly shown CD4 count less than 50 cells/μL independently predicts mortality in TB/HIV coinfection." (PMID 25966339, 2015). "Patients with chronic hepatitis secondary to HIV/HVC coinfection had higher CD4+ T cell count at inclusion than those with HIV monoinfection and those with liver cirrhosis." (PMID 25775475, 2015). "The result revealed that antihelminthic treated participants showed an increase of CD4+ T-cell count in Ascaris lumbricoides/HIV co-infection with significant difference(P = 0.02)." (PMID 26415705, 2015). "The result revealed that higher CD4+ T-cell count was observed in Ascaris lumbricoides/HIV co-infection (P = 0.05) after therapy." (PMID 26415705, 2015). "Secondly, individuals with HCV co-infection will have slower CD4 cell count recovery following cART initiation, regardless of duration of HCV infection duration." (PMID 26225723, 2015). "Host immune factors most frequently examined were HIV co-infection (10/32) and CD4 lymphocyte count in HIV-infected patients (8/32)." (PMID 26406228, 2015). "The following factors were identified as significant contributors of TB disease among inmates: age 21–30 years, HIV coinfection, BMI ≤18.5 kg/m2, CD4 cell count ≤350 cells/mm3, smoking (ex-smoking), previous TB history, and substance abuse." (PMID 25866677, 2015). "The effects of HIV-1 co-infection and the influence of CD4+ cell numbers on these clinical manifestations of chronic S. mansoni are not known." (PMID 25948238, 2015). "The general effect of CMV co-infection status was most notable in the CD8+ population of T-cells with little impact on the CD4+ T-cell populations." (PMID 25794163, 2015). "The independent predictors of mortality include single marital status, being illiterate, bedridden functional status, advanced WHO status, low BMI, low CD4 count, severe anemia and TB co-infection." (PMID 26889319, 2015). "There is no clear association between chronic HCV and HIV disease progression, but HCV co-infection can impair cellular immunity, independent from CD4 cell count." (PMID 25690530, 2015). "HIV co-infection was associated with an increased frequency of CMV-specific IFN-γ-only and TNF-α-only CD4+ cells compared with PPD." (PMID 26417433, 2015).
co-infection (continued). "At baseline, patients with NADC, respect to those with ADC and those without cancer, were older, had a higher proportion of intravenous drugs users (IDUs), HBV or HCV co-infection, and an intermediate CD4 cell count mean." (PMID 25884678, 2015). "In this study, we focused on the impact of co-infection on CD4+ T cells, which are a critical cell type for immunity to H. polygyrus and contribute significantly to anti-malarial immunity." (PMID 26147567, 2015). "We studied the effect of a lowering of CD4 level on co-infection in this HIV infected population by stratifying our study subjects into those with a CD4 count of below 250 cells/μl and those with CD4 counts ≥250 cells/μl." (PMID 26371878, 2015). "In this study, we identified that Plasmodium infection significantly reduced CD4+ Th2 cells during co-infection with H. polygyrus and that anti-helminth immunity was compromised during co-infection." (PMID 26147567, 2015). "The lower CD4+ T-cell count value in hookworm/HIV co-infection was also recorded in the study participants after 6 months post-anhelminthic treatment." (PMID 26415705, 2015). "Compared to other pathogens, MTB-specific T-cells were uniquely impacted by HIV co-infection, as there was attenuation of the frequency of the CD4+ IFN-γ and IL-2-dual response." (PMID 26417433, 2015). "One of the major impact of HCV coinfection is the persistent low CD4+ T cell counts in HIV/HCV co-infected compared to HIV mono-infection individuals." (PMID 25528160, 2014). "For HCV co-infection, the CD4 count was 308 cells/μL at one year of ART, 374 cells/μL at three years and 448 cells/μL at five years of ART." (PMID 24533106, 2014). "With regards to HBV co-infection, CD4 count recovery was less pronounced, and a 60% increase in mortality was observed throughout the follow-up period." (PMID 24533106, 2014). "The correlation of different phenotypes of Ag-specific-CD4 T cells, and their role on the protection or susceptibility to infection, has been clearly demonstrated by the emerging characterization of polyfunctional CD4 T cells in TB-HIV co-infection." (PMID 24795723, 2014). "Conversely, HMOX1 expression was lowest in patients with HIV/HCV co-infection, especially those with lower CD4 lymphocyte counts and higher HIV viral loads, which is disadvantageous." (PMID 24752012, 2014). "Similar to a previous report, mice conditionally for IL-10 production by CD4 T cells had a trend for lower parasitemia during co-infection." (PMID 24787713, 2014). "Estimated effect of hepatitis B or C co-infection on CD4 count change after initiation of antiretroviral treatment." (PMID 24533106, 2014). "In logistic regression adjusted for age group, duration with HAART, BMI, CD4+ cell count, and TB-HIV co-infection, HAART initiation was significantly associated with serum TC, HDL-C and LDL-C levels." (PMID 24950924, 2014). "The same study confirmed that lower CD4 cell counts, HIV viral replication and HBV co-infection are all risk factors for liver-related death." (PMID 25253564, 2014). "In the two different S. japonica schemes, mice in the co-infection-100c group had significantly lower levels of CD4+ and CD8+ T cells on days 3, 5 and 8 pi when compared to P. berghei-mono group." (PMID 24670210, 2014). "Recent clinical trials have provided clear evidence to support early anti-retroviral therapy (ART) in patients with HIV/TB co-infection and low CD4 counts." (PMID 25394128, 2014). "Prolonged incubation periods with old world CL have previously been described and and low CD4 cell subsets have been recognized as a risk factor for recurrence in HIV-1 and L. infantum co-infection." (PMID 25428722, 2014). "In total, 97% of our patients with coinfection were receiving cART for a long time (a median of 145 months) and 74% had undetectable viral load and a good immunological control (median CD4/mmc of 547)." (PMID 25337140, 2014).
co-infection (continued). "Eight variables remained in the final model, of which only five predictive factors were strongly associated with M. tuberculosis/HIV co-infection including imprisonment, previous TB infection, IPT, ART, and reduced CD4 cell count." (PMID 25358465, 2014). "All patients reported with PKDL and HIV co-infection had a CD4 count of less than 350 mm3; in 95% this count was less than 200 mm3." (PMID 25412435, 2014). "On the other hand, there was a strong association between M. tuberculosis/HIV co-infection and imprisonment, previous TB infection, IPT, ART, and CD4 cell count less than 350 cells/mm3." (PMID 25358465, 2014). "Our data on STR/TB co-infection also reveals remarkably similar yet more pronounced effects of helminth infection on CD4+ T cell responses in active TB." (PMID 25211342, 2014). "It was reported that IL-27 was negatively correlated with HIV viral load, downregulated under HCV co-infection, and related to the CD4+ T cell counts." (PMID 24816922, 2014). "Some authors have identified coinfection with HIV and the degree of immunosuppression as a risk factor of mortality in IVDU patients with IE, particularly in patients with CD4 cell counts <200/mm3." (PMID 24661344, 2014). "Although the cART regimen significantly restores CD4+ T cells in HIV mono-infection but the data are conflicting for HIV/HCV co-infection." (PMID 25528160, 2014). "Further, HCV co-infection has been shown to negatively impact CD4+ T cell reconstitution following HAART." (PMID 25528160, 2014). "In adjusted analysis, a significant lesser increase in CD4 count was estimated for HBV co-infection." (PMID 24533106, 2014). "Individuals with HIV-HBV, HIV-HCV and HIV-HBV-HCV co-infection also had a lower mean CD4 levels than HIV mono-infected study participants." (PMID 23721493, 2013). "In light of this evidence suggesting recent, primary MDR-TB infection, high rates of HIV co-infection and low CD4 counts, the extensive pathology seen on chest radiographs in this cohort is surprising." (PMID 24040132, 2013). "To investigate the effect of CCL3L1 copy number on viral load, immediately prior to HAART, we fitted a generalised linear model to the data, with population of origin, tuberculoisis co-infection status and CD4+ count immediately prior to HAART as cofactors." (PMID 24219137, 2013). "HIV co-infection was documented in 280 (80%) participants with 78% of them having CD4 counts < 200 cells/mm." (PMID 23497232, 2013). "In contrast, co-infection of HIV and B. hominis was associated with higher CD4+ T lymphocyte levels." (PMID 23971713, 2013). "We evaluated the impact of HCV co-infection on recovery of CD4+ and CD8+ T-cells and liver enzyme levels before and after initiation of highly active antiretroviral therapy (HAART) in HIV/HCV co-infected patients." (PMID 23679118, 2013). "Our finding indicates that in HIV coinfection, M. tuberculosis-antigen-specific CD4+ cells lose CD127 expression with advancing HIV disease and are therefore potentially more differentiated." (PMID 23966657, 2013). "In the context of EBV infection and HL development, EBV-specific CD4 cell responses rapidly decline with HIV co-infection, dampening EBV clearance." (PMID 24098586, 2013). "Such high values of mean CD4 count in HIV-HCV co-infected study participants than study participants who had HIV-HBV co-infections were unclear." (PMID 23721493, 2013). "Vitamin D deficiency was noted to be more common among patients with hypocalcaemia corrected for albumin concentration (67%), HIV co-infection (82.6%), CD4 counts < 200 cells/μl (83.2%), anemia (86.1%) and hypoalbuminemia (97.4%)." (PMID 23886009, 2013). "While the frequencies of CD4 T cells were, except from the spleen, significantly decreased upon co-infection with PbNK65, frequencies of CD8 T cells were significantly increased, resulting in a reversed CD4/CD8 T cell ratio." (PMID 23110184, 2012).